IL13 (interleukin 13)
Diseases named in the same sentence as IL13 in open-access papers (continued):
Sharing a sentence is not in itself a finding about the gene and the disease.
atopic dermatitis (continued). "Background/Objectives: Dupilumab is an interlekin-4 receptor antibody that exerts its efficacy by inhibiting the signaling pathway of interleukin-4/interleukin-13, and it is currently used clinically as a highly potent therapeutic for atopic dermatitis." (PMID 39997051, 2025). "Our findings in the goat AD model demonstrate a Th2-dominant immune response, with elevated IL-4 and IL-13 cytokine expression, which closely mirrors observations in human and murine models of atopic dermatitis." (PMID 39943182, 2025). "We find that in RAG-deficient mice, ILC2 populations expand and produce increased IL-5 and IL-13 at steady state and contribute to increased inflammation in atopic dermatitis (AD)-like disease." (PMID 38712036, 2025). "Background/Objectives: Tralokinumab, a fully human monoclonal antibody targeting IL-13, has shown efficacy and safety in clinical trials and real-life studies for atopic dermatitis (AD)." (PMID 40142885, 2025). "Atopic dermatitis (AD) is a chronic inflammatory skin disease characterized by epidermal barrier dysfunction and immune dysregulation, with interleukin (IL)-4, IL-13, and IL-31 recognized as key mediators." (PMID 40364058, 2025). "Dupilumab is a human monoclonal antibody targeting the Th2 immune axis by inhibiting IL-4 and IL-13 and has shown efficacy for moderate to severe atopic dermatitis and sporadic cases of NE in adults." (PMID 40264610, 2025). "Although both TH2 cells and group 2 innate lymphoid cells are considered as the primary cellular sources of IL-4 and IL-13 in atopic dermatitis skin, mast cells also contribute to the elevated levels of these TH2 cytokines." (PMID 39890627, 2025). "Dupilumab, a human monoclonal antibody that targets both IL-4 and IL-13, has shown efficacy for moderate to severe atopic dermatitis and other immune-mediated disorders." (PMID 40264610, 2025). "Pearson correlation analysis between serum IAP, I‐FABP, TFF‐3, IgE, IL‐4, IL‐13, monocyte and eosinophil parameters in dogs with atopic dermatitis." (PMID 38648253, 2024). "Atopic dermatitis is defined as an immune disorder driven by Th2 cells and characterized by elevated levels of interleukin (IL)-4, IL-13, and IL-5." (PMID 38541664, 2024). "We established an in vitro model of atopic dermatitis-like barrier disruption by treating human keratinocytes with IL-4 and IL-13, two key cytokines involved in Th2 inflammation." (PMID 39329899, 2024). "For example, in atopic dermatitis and bronchial asthma patients, increased SCCA is caused by IL-4 and IL-13, which are secreted by Th2 cells." (PMID 38347831, 2024). "Atopic Dermatitis is largely a Th2-driven disease that is characterized by elevated levels of interleukin (IL)-4, IL-5, IL-13, and IL-31." (PMID 39119011, 2024). "An increase in Th2 cytokines, including IL-4 and IL-13, is an important feature in atopic dermatitis lesions." (PMID 39599592, 2024). "Nevertheless, it serves as an initial exploration for future studies, being among the first, to our knowledge, to assess IL-4 and IL-13 as biomarkers for atopic dermatitis." (PMID 38541676, 2024). "In the present study, a statistically significant increase in serum IL‐4 (p < 0.001) and IL‐13 (p < 0.001) concentrations was determined in dogs with atopic dermatitis, compared to the healthy ones." (PMID 38648253, 2024). "Atopic dermatitis (AD) is an allergic skin disease mediated by skin barrier impairment and IL-13-driven immune response." (PMID 38344408, 2024). "Upon the IL-4/IL-13 treatment, the epidermis exhibited a thinned and unpacked morphology resembling the skin barrier disruption observed in atopic dermatitis." (PMID 39329899, 2024). "Tralokinumab, a humanized monoclonal antibody targeting interleukin-13, has been primarily used for the treatment of moderate-to-severe atopic dermatitis." (PMID 39193341, 2024).
atopic dermatitis (continued). "In the initial and acute phase of Atopic Dermatitis (AD), a Th2-based immune response (IL-4, IL-13, thymic stromal lymphopoietin, and eosinophils) is typically observed." (PMID 39119011, 2024). "Lebrikizumab, an IL-13 immunomodulator, has shown recommendable effectiveness and safety in clinical studies for the treatment of moderate-to-severe atopic dermatitis (AD) in adolescents and adults." (PMID 39629076, 2024). "It inhibits the signaling of IL-4 and IL-13, which drive inflammatory skin conditions, like atopic dermatitis." (PMID 39507480, 2024). "In our investigation, we assessed the potential of IL-4 and IL-13 as biomarkers for gauging the treatment response in patients with atopic dermatitis (AD) undergoing Dupilumab administration." (PMID 38541676, 2024). "Known biomarkers of atopic dermatitis include IL-22 (Interleukin-22), IL-18, and IL-13, as well as eosinophilia and elevated IgE levels." (PMID 39457662, 2024). "The immunology of chronic prurigo shows similarities with atopic dermatitis due to the involvement of IL-4 and IL-13, IL-22, and IL-31." (PMID 38493053, 2024). "Another antibody that binds to IL-13 is Tralokinumab, approved for the treatment of moderate to severe atopic dermatitis from the age of 12 years." (PMID 38672221, 2024). "To further investigate the function of dhAvD in the whole skin model, we used a reconstructed human skin model (RHS) treated with IL-4 and IL-13, which are known to induce atopic dermatitis-like conditions." (PMID 39329899, 2024). "Intrinsic atopic dermatitis is characterized by a normal skin barrier, lower expression of IL-4, IL-5, and IL-13, and higher expression of IFN-gamma." (PMID 38672221, 2024). "Atopic dermatitis is characterized by the release of T-helper 2 (Th2) cytokines IL-4 and IL-13 and T-helper 17 (Th17) cytokines IL-17, IL-22, and interferon (IFN)-γ (chronic eczema)." (PMID 39062477, 2024). "In our investigation, we conducted a clinical assessment of IL-4 and IL-13 as potential biomarkers for disease severity and the treatment response in atopic dermatitis (AD)." (PMID 38541676, 2024). "IL-4 and IL-13 are closely related to atopic dermatitis, and they activate the intracellular JAK1/STAT6 pathway." (PMID 39599592, 2024). "Increased concentrations of IL‐4, IL‐12, IL‐13 and IL‐18 have been found in humans with atopic dermatitis." (PMID 38648253, 2024). "In support, a mouse model found that diet-induced obesity increased the severity of atopic dermatitis in an IL-17 dependent manner, and that rosiglitazone suppressed IL-17 and restored the effectiveness of anti-IL-4 and anti-IL-13 therapy." (PMID 39763655, 2024). "Serum concentrations of IAP (p < 0.01), TFF‐3 (p < 0.01), IgE (p < 0.01), IL‐4 (p < 0.01) and IL‐13 (p < 0.01) were significantly higher in dogs with atopic dermatitis, compared to the healthy ones." (PMID 38648253, 2024). "In atopic dermatitis pathogenesis, inflammatory cytokines of the Th2, Th17, Th1, and Th22 subclasses, such as IL-4, IL-13, IL-17A, INF-γ, IL-12A, and IL-22, play important roles." (PMID 38672764, 2024). "Tralokinumab exerts its therapeutic effects by neutralizing the activity of IL-13, a crucial cytokine in the inflammatory cascade of atopic dermatitis." (PMID 39193341, 2024). "In the context of eczematous dermatitis, the inflammatory milieu is often dominated by a Th2‐driven immune response, characterized by cytokines such as IL‐4, IL‐5, and IL‐13." (PMID 39670074, 2024). "As previously reported, the increase in serum IL‐4 and IL‐13 concentrations in dogs with atopic dermatitis in this study may indicate that the cytokine response to allergens in atopic dermatitis caused by environmental allergens in dogs is mainly mediated by IL‐4 and IL‐13." (PMID 38648253, 2024). "Abrocitinib, an oral JAK1 inhibitor, that curtails the signaling of IL-4 and IL-13, has been reported to provide early itch symptom relief in the atopic dermatitis." (PMID 38541674, 2024).
atopic dermatitis (continued). "Dupilumab, an antibody blocking IL-4 and IL-13, is approved for treating moderate to severe atopic dermatitis (AD) where itching is a significant symptom." (PMID 38846700, 2024). "Lebrikizumab is a new monoclonal antibody that targets IL-13 which inhibits the formation of the signaling complex of the IL-13Rα1/IL-4Rα receptor in adult patients with moderate to severe atopic dermatitis." (PMID 36983094, 2023). "The expression of Il4, Il13, and Il33 was increased in the skin of NC/Nga mice with atopic dermatitis, while calcitriol application decreased Il13 and Il33 mRNA expression." (PMID 37298299, 2023). "Dupilumab, a prominent therapy targeting IL-4 and IL-13, has demonstrated well-documented efficacy, tolerance, and safety in atopic dermatitis." (PMID 38203533, 2023). "Cells under atopic dermatitis conditions (IL-4 and IL-13) showed decreased decline in scratch width in HaCaTs (65.2 ± 2.9%) and primary keratinocytes (54.0 ± 1.8%) compared to controls after 48 h." (PMID 36615633, 2023). "Our finding is consistent with recently published data reporting an increase in transcripts related to atopic dermatitis, inflammation, and itch after IL-13 stimulation in human DRG cultures." (PMID 37868811, 2023). "We also found nectin-1 ubiquitously localized in the epidermis of atopic dermatitis and IL-4/IL-13-treated human skin implying that impaired tight-junctions in combination with a defective cornified layer allow the accessibility of nectin-1 to HSV-1." (PMID 37289055, 2023). "We also observed viral invasion via the skin surface after IL-4/IL-13 stimulation of human skin from healthy individuals, which was less efficient than in atopic dermatitis skin." (PMID 37289055, 2023). "Different JAKs are involved in the signal transduction of numerous cytokines and growth factors, including IL-4 and IL-13, the main mediators of atopic dermatitis." (PMID 37834935, 2023). "Recent evidence suggests that interleukin (IL)-13 is a crucial cytokine involved in the pathogenesis of atopic dermatitis (AD)." (PMID 37144036, 2023). "The enrichment of the immune pathways was also high in atopic dermatitis or psoriasis, but the IL-3/IL-5/GM-CSF and IL-4/IL-13 signaling was highest in HS lesional skin." (PMID 38069342, 2023). "Calcitriol administration attenuated the expression of Il13 and Il33 in the skin of NC/Nga mice with atopic dermatitis compared to vehicle-treated mice." (PMID 37298299, 2023). "Periostin has been shown to play a role in Th2 pathway-mediated inflammatory diseases, such as atopic dermatitis, where interleukin-4 and interleukin-13 cytokines have been reported to activate periostin production in fibroblasts." (PMID 37773198, 2023). "Cutaneous afferent neurons express receptors interleukins (IL)-4, IL-13, and IL-33, which are type 2 cytokines that are elevated in atopic dermatitis." (PMID 37868811, 2023). "Dupilumab is a monoclonal antibody that targets the IL-4α receptor and improves the symptoms of atopic dermatitis by inhibiting IL-4 and IL-13." (PMID 38482457, 2023). "Ocular surface diseases, including conjunctivitis, are recognized as common comorbidities in atopic dermatitis (AD) and occur at an increased frequency in patients with AD treated with biologics targeting IL-4 receptor α (IL-4Rα) or IL-13." (PMID 36626228, 2023). "We also demonstrated that induced Th2 immune responses, which mimic an atopic dermatitis-like phenotype, can lead to successful viral penetration as shown by infected cells in interleukin-4 (IL-4)/IL-13-treated human skin." (PMID 37289055, 2023). "In atopic dermatitis, or eczema, the main role is played by T-helper 2 cells and an upregulation of IL-4 and IL-13 is found, in addition to interferon (IFN)-γ, IL-17, and IL-22 in chronic eczema." (PMID 36770889, 2023). "Atopic dermatitis generally occurs due to an abnormal increase in the levels of Th2 cytokines such as IL-4, IL-5, and IL-13." (PMID 37432237, 2023).
atopic dermatitis (continued). "We observed an increased mRNA expression of type 2 inflammatory mediators, including interleukin-4 (Il4), Il13, and Il33, in the skin of NC/Nga mice with atopic dermatitis compared with control mice." (PMID 37298299, 2023). "IL-13 is also increased in atopic dermatitis and is a potent enhancer of neuronal responses of pruritus and neurogenic inflammation." (PMID 36561717, 2022). "IgG autoantibodies against IgE from atopic dermatitis can induce the release of IL-4/IL-13 and LTC4 from human basophils, indicating that these cells contribute to this allergic disorder." (PMID 36578500, 2022). "Atopic dermatitis (AD), driven by interleukins (IL‐4/IL‐13), is a chronic inflammatory skin disease characterized by intensive pruritus." (PMID 35111948, 2022). "IL-4, IL-9 and IL-13 cytokines represent some of the main effectors in the pathogenesis of atopic dermatitis." (PMID 35163615, 2022). "Other biologics currently under investigation for the treatment of atopic dermatitis include the IL-13 inhibitors lebrikizumab and tralokinumab, with the latter agent now approved in Europe." (PMID 36552866, 2022). "Preclinical studies of IL-13-stimulated HaCaT cells have shown that rapamycin can mediate this pathway and ease the effects of IL-13 in atopic dermatitis." (PMID 35163615, 2022). "The targeted inhibition of effector cytokines such as interleukin 17 (IL-17) in psoriasis and IL-13 in atopic dermatitis offers impressive efficacy with a favorable side effect profile." (PMID 35967358, 2022). "Th2 cells mediate inflammation in atopic dermatitis with the release of IL-4 and IL-13, which contribute to clinical manifestations." (PMID 36578500, 2022). "An important biologic for the treatment of atopic dermatitis is dupilumab, an IL-4 receptor-α inhibitor that blocks both IL-4 and IL-13 activity and is approved for the treatment of moderate-to-severe atopic dermatitis in patients 6 years of age and older." (PMID 36552866, 2022). "Atopic dermatitis is associated with T-cells exhibiting a Th2 polarized phenotype, with increased expression of Th2 cytokines, such as IL4, Il5, and IL13." (PMID 34445339, 2021). "First, to validate that introduction of Th2 related cytokines (IL-4, IL-13, and IL-25) can stimulate atopic dermatitis environment, we looked at differentially expressed genes with p-value < 0.005." (PMID 33806193, 2021). "In a murine model of atopic dermatitis, where IL-13 is overproduced, an IL-13 ASO administered topically using liposomes significantly suppressed the IL-13 production up to 70% compared to the control group." (PMID 34684016, 2021). "Recent data in atopic dermatitis patients undergoing dupilumab treatment (IL-4 and IL-13 blocker) reported the development of peripheral enthesitis." (PMID 33544244, 2021). "Monoclonal antibodies (mAbs) targeting IL-4Ra, such as dupilumab, ameliorate atopic dermatitis by blocking both IL-4 and IL-13 signaling." (PMID 34305927, 2021). "Dupilumab is a dual inhibitor of interleukin-4 and interleukin-13 and is mainly used to treat moderate-to-severe atopic dermatitis." (PMID 34253801, 2021). "The JAK1 inhibitor abrocitinib, which reduces IL-4 and IL-13 signaling, is being investigated for the treatment of atopic dermatitis." (PMID 34680614, 2021). "In an IL-13-induced mouse model of atopic dermatitis, blocking the TRPA1 led to a reduction of the scratching response." (PMID 34439832, 2021). "Atopic dermatitis (AD) is an eczematous, pruritic skin disorder with extensive barrier dysfunction and elevated interleukin (IL)-4 and IL-13 signatures." (PMID 32751111, 2020). "In atopic dermatitis, cytokines IL-4 and IL-13 play a key role in the modulation of the epidermal barrier and the stimulation of dermal inflammation and remodeling." (PMID 32382467, 2020). "Dupilumab, targeting the interleukin-4α receptor and inhibiting the action of interleukin-4 and interleukin-13, was recently approved for treatment of moderate to severe atopic dermatitis." (PMID 32962676, 2020).
atopic dermatitis (continued). "IL-13 is expressed in atopic dermatitis skin lesions and plays an important role in pathogenesis of the disease." (PMID 32179159, 2020). "Especially, antibodies against IL-4 and IL13 have been investigated as molecular targets for moderate-to-severe atopic dermatitis." (PMID 32375285, 2020). "Patients on immunosuppressive therapy for severe atopic dermatitis should be strictly monitored or transitioned to safer anti-IL4/IL13 immune-modulatory agents, as advocated by the European Task Force on atopic dermatitis." (PMID 32566128, 2020). "For instance, as described in atopic dermatitis, T helper type 2-produced cytokines (especially IL-4 and IL-13) affect keratin, desmoglein, loricrin and involucrin levels." (PMID 32119674, 2020). "In atopic dermatitis (AD), Th2 cytokines such as IL-4 and IL-13 are regarded to be the main player of the disease; however, Th17 cytokines are also expressed in AD skin lesions." (PMID 32075269, 2020). "To date, the most successful treatment for atopic dermatitis is dupilumab, an antibody that regulates two signaling pathways (the IL-4 and IL-13 pathways) by binding to a receptor called IL-4Ra." (PMID 31782733, 2019). "For instance, from deeply-sequenced RNA samples using long paired-end reads, a recent study reported that atopic dermatitis was an IL-13-dominated disease." (PMID 31781276, 2019). "Dupilumab, a monoclonal antibody directed against IL-4 and IL-13, developed for atopic dermatitis interferes with key cytokines in the Th2 pathway and offers new possibilities for off-label use." (PMID 31440261, 2019). "Among potential targets, interleukin 13 (IL-13) merits consideration, as monoclonal antibodies disrupting IL-13 signaling are proving to be exceedingly effective in common conditions such as atopic dermatitis." (PMID 30759882, 2019). "The vicious itch–scratch cycle is a cardinal feature of atopic dermatitis (AD), in which IL-13 signaling plays a dominant role." (PMID 31284553, 2019). "The activation of T2 cells leads to IL-4, IL-5, and IL-13 secretion, provoking skin barrier alteration, immune cell infiltration into skin, and itch as observed in atopic dermatitis." (PMID 31028434, 2019). "Atopic dermatitis increased the expression levels of IL-4, IL-13, IL-6, IL-17, IFNγ, and TNFα but decreased the expression of IL-10 in BALB/c mouse, in an SOCS1-dependent manner." (PMID 30459600, 2018). "Fibroblast proliferation and activation are increased in atopic dermatitis patients skin samples, as well in IL-13-induced atopic dermatitis mice." (PMID 28779153, 2017). "While much has been published on the effects of excessive expression of IL-4/IL-13 on the skin barrier in inflammatory skin diseases such as atopic dermatitis (AD), the potential role of constitutive expression of IL-13 has hitherto been less well understood." (PMID 27357235, 2016). "For example, expression of this channel has also been observed in cutaneous mast cells, where it is upregulated in the interleukin 13 overexpression mouse model of atopic dermatitis." (PMID 27983625, 2016). "High levels of TSLP, but also of IL5 and IL13 have been reported in the skin of atopic dermatitis patients, particularly in those with elevated IgEs." (PMID 27431613, 2016). "Atopic dermatitis has been thought as a typical Th2 type immune disorder that expresses high levels of Th2 type cytokines such as IL-4, IL-5, and IL-13." (PMID 24499290, 2013). "We included the type 2 cytokine IL-13 in our study because IL-31 mRNA expression in skin samples of patients with atopic dermatitis or allergic contact dermatitis was reported to be correlated with IL-13 levels." (PMID 22853438, 2012). "Atopic dermatitis is thought to be a typical Th2 type immune disorder which shows elevated serum IgE level and increment of Th2 type cytokines such as IL-4, IL-5 and IL-13." (PMID 22988890, 2012). "The percentage of CD4+ IL-13+ T cells has been shown to correlate significantly with the severity of atopic eczema in children." (PMID 22013915, 2011).